RN7SL554P (RNA, 7SL, cytoplasmic 554, pseudogene)
Gene: Miscellaneous RNA gene on chromosome 6 (6,938,606 to 6,938,897, reverse strand). Ensembl gene ENSG00000240936.
Homologues: Orthologues: chimpanzee Metazoa_SRP (96% identical), macaque Metazoa_SRP (91% identical). Paralogues in human: RN7SL1 (83% identical), RN7SL113P (83% identical), RN7SL2 (83% identical), RN7SL431P (82% identical), RN7SL220P (82% identical), RN7SL3 (81% identical), RN7SL566P (81% identical), RN7SL680P (80% identical), RN7SL712P (80% identical), RN7SL118P (79% identical), RN7SL296P (79% identical), RN7SL45P (79% identical), and 701 more.